IL6 (interleukin 6)
Diseases named in the same sentence as IL6 in open-access papers (continued):
Sharing a sentence is not in itself a finding about the gene and the disease.
Stroke (continued). "The level of serum IL-6 can reflect the degree of brain ischemic damage and correlates with stroke lesion volume." (PMID 27661079, 2016). "We found that aged isolated male mice had significantly increased infarct volume, neurological deficits, and serum IL-6 levels three days after stroke compared to pair housed (PH) mice." (PMID 27125783, 2016). "A two-fold increase in plasma IL-6 levels was seen 72 hours after stroke in the ST-ISO group compared to ST-PH group (P < 0.05)." (PMID 27125783, 2016). "A decreased IL-6 level has been found in post-mortem brain tissue from post-stroke dementia patients." (PMID 27275837, 2016). "IL-6 rose significantly at 6 hours after stroke in both young (p<0.001) and aged (p<0.0001) mice compared to sham values." (PMID 27115295, 2016). "TNF-α is involved in the process of ischemic injury, and increased IL-6 has been found in the adverse prognosis after stroke." (PMID 27211606, 2016). "The data showed that the anti-TLR2 antibody is able to decrease the expression of IL-17, IL-6 and IL-33, and IL-17 and IL-33 are highly increased in stroke patients." (PMID 27040385, 2016). "Cytokines, including TNF‐α, IL‐1, and IL‐6, are greatly produced by microglia in the brain after experimental stroke." (PMID 27781140, 2016). "Sieber and collegues previously showed that increases of TNFα, IL-1β, MIP-1α, MCP-1, and IL-6 are attenuated 7 days following stroke in aged C57BL/6 mice, and that older mice have smaller infarct volumes." (PMID 27600707, 2016). "Recently, it was reported that treatment with AMD3100 after experimental stroke reduce IL-6 levels as well as other proinflammatory cytokines." (PMID 27230771, 2016). "As expected, stroke cases had increased levels of both serum IL6 and CRP compared to the control group; P < 0.01." (PMID 26945394, 2016). "In this study, the mRNA expressions of inflammatory cytokines TNF-α, IL-1β, iNOS, and IL-6 in ipsilateral brain cortex were detected at different time points after stroke." (PMID 25889216, 2015). "Generally, expressions of the cytokines were increased soon after stroke and peaked at 24 h (IL-1β, IL-6, TNF-α) or 48 h (iNOS) post-MCAO." (PMID 25889216, 2015). "The mRNA levels of IL-1β and IL-6 in infarct-side brain tissue were increased on day 1 and decreased on day 4 after stroke onset." (PMID 26059659, 2015). "In fact, plasma and cerebrospinal fluid levels of IL-6 correlate with stroke severity and poor clinical outcome in patients and reduced blood concentrations of this cytokine have been correlated to the improved outcome induced by treatment with IL-1ra." (PMID 25972779, 2015). "Although IL-6 is a ubiquitous cytokine, it has been demonstrated that its production is higher within 72 h of stroke onset, and it has a key role at this stage of inflammatory response." (PMID 26543408, 2015). "After the acute event of stroke, concentrations of the pro-inflammatory cytokine IL-6 and the acute phase protein CRP in brain tissue and peripheral blood are increased since they are rapidly released by activated cells." (PMID 25613713, 2015). "When mice were treated with ibrutinib or PBS on day 0, mature IL-1β protein levels on day 1 after stroke onset were much lower in the brain lysates of ibrutinib-treated mice than in control mice, whereas the IL-6 and TNF-α protein levels were similar." (PMID 26059659, 2015). "Experimental stroke leads to an increase in circulating CD11b+ monocytes which can secrete inflammatory cytokines such as IL- 1β, IL-6, TNFα that maintain the inflammatory response and result in tissue-specific monocyte homing." (PMID 26634148, 2015). "The increase in brain chemokine expression observed here is in contrast to that in mice fed a high-fat ‘diabetic’ diet where a blunted chemokine (CCL2) and cytokine (interleukin-6) response after stroke is observed." (PMID 26239227, 2015).
Stroke (continued). "IL-1β and IL-6 stimulate Th17 and Treg cell differentiation, and circulating levels of these cytokines in the acute phase after stroke predict the severity of PSF and poststroke depression (PSD) months thereafter." (PMID 26166952, 2015). "Our finding of attenuated stroke-induced inflammatory response in diabetic mice is also consistent with literature showing attenuated LPS-stimulated IL-6 levels and hypoxic/ischemia-induced cytokine in diabetic conditions." (PMID 24886035, 2014). "in stroke patients, IL-6 correlated significantly with clinical severity (APACHE II scale), stroke severity (NIHSS scale), infarct volume (cm3) and clinical outcome (mRS) (r = 0.326, 0.497, 0.290 and 0.444 respectively; P < 0.05)." (PMID 25086655, 2014). "In stroke patients, correlations were found between IL-6 at <12 h and clinical severity in the case of patients with large infarcts." (PMID 25086655, 2014). "It is well known that IL-6 is associated with END, greater infarct volumes and poor outcomes in stroke patients." (PMID 25086655, 2014). "IL-6 at 72 h correlated with clinical severity, stroke severity, volume of infarct and 3-month mRS in all stroke patients, as well as with stroke severity in patients with medium-sized infarcts." (PMID 25086655, 2014). "IGF-1 induced Akt activation was preceded by a reduction of blood brain barrier permeability at 4h post-stroke and global suppression of cytokines including IL-6, IL-10 and TNF-α." (PMID 24618563, 2014). "Treatment with rt-PA starting with administration at 20 min after stroke reduced the stroke-induced activation of IL-6, TNF-α, Caspase 3, hsp 32, hsp 70 and MMP-9 significantly in the MCAO." (PMID 24465746, 2014). "Consistent with these earlier in vitro studies, we found that knockout of CaMKK β or CaMK IV increased TNFα and IL-6 production in mice after stroke." (PMID 25331941, 2014). "We observed that the IL-23, IL-6, and IL-1β plasma levels were increased in IS patients at 7 and 28 days after stroke compared with controls." (PMID 24991091, 2014). "Brain cytokine analysis at 24 h indicated that stroke resulted in substantially higher mean levels of IL-4, IL-6, TNF-α, IFN-γ, IL-10, and IL-17A in both C57Bl/6 and FVB mice." (PMID 25477780, 2014). "In recent years, there has been a propensity to understand the role of inflammatory factors, especially IL-6 in the stroke." (PMID 25295149, 2014). "On the contrary, however, there are some reports unable to demonstrate the role of IL-6 in stroke patients." (PMID 25295149, 2014). "Even in medium-sized brain infarction, IL-6 levels correlated with stroke severity, confirming the predictor value of this cytokine in ischemic stroke patients." (PMID 25086655, 2014). "Consistent with previous stroke studies, we also observed an increase in several brain inflammatory cytokines including IL-6, TNF-α, IL-1β in the ischemic hemisphere of vehicle treated animals." (PMID 24618563, 2014). "In our results, IL-6 levels increased over time in stroke patients and were correlated with clinical severity, stroke severity, infarct volume and long-term clinical outcomes." (PMID 25086655, 2014). "• Combination of blood markers including IL-6 and hFABP improved the predictive value of clinical predictors for stroke outcome." (PMID 23497639, 2013). "In the periphery after stroke, systemic activation of the immune system occurs with increased levels of cytokines such as IL-1β, IL-6, TNF-α, IL-10, IL-17, and transforming growth factor (TGF)-ß." (PMID 23936327, 2013). "From 0–2 days after stroke (hyperacute phase), IL-6 and IL-17A levels showed positive correlations with overall monocyte counts (r=0.556, p<0.001, and r=0.597, p=0.001, respectively; Spearman’s rank correlation coefficient, data not shown)." (PMID 23936327, 2013). "The addition of the IL-6 and hFABP levels improved the prognostic performance of the clinical predictors for stroke outcome." (PMID 23497639, 2013).
Stroke (continued). "This prompted us to analyze in greater detail the expression levels of well-defined pro-inflammatory mediators during stroke, namely interleukin-6 (IL-6), CD68, CCL3 (MIP1α), and CCL5 (RANTES) by means of rt-PCR." (PMID 24024100, 2013). "In our data, the combined use of IL-6 and hFABP significantly improved the discriminating ability of the clinical model poor stroke outcome." (PMID 23497639, 2013). "That of IL-6 seemed to reflect the status of complicated infection, as it reached a peak from 0–7 days after stroke and rapidly decreased to an unremarkable level in patients with SAI." (PMID 23936327, 2013). "Among the large number of cytokines, TNF-α, IL-1 and IL-6, modulate tissue injury in experimental stroke and are therefore potential targets in stroke therapy." (PMID 23514014, 2013). "CRP, IL-6, white blood cells (WBCs), mean body temperature and National Institutes of Health Stroke Scale (NIHSS) score were measured at the time of admission." (PMID 23935729, 2013). "Our results are consistent with previous studies which showed that IL-6 lacks clinical usefulness in the discrimination and reclassification between favorable and poor outcome groups of stroke patients." (PMID 23497639, 2013). "A combination of circulating IL-6 and hFABP level has an additive clinical value for the prediction of stroke outcome." (PMID 23497639, 2013). "A systematic study of IL-6 expression in an experimental animal stroke model demonstrated that immunoreactivity of IL-6 was highest in the peri-ischemic regions and suppressed in the central infarct region." (PMID 23520526, 2013). "After the acute event of stroke, the proinflammatory cytokine IL-6 is rapidly released by activated cells in brain tissue and peripheral blood." (PMID 23158556, 2012). "ADMA levels at the time points 12 and 24 hours, 3 and 7 days, IL-6 levels at 6, 12 and 24 hours, and S100B levels at all time points were higher in stroke patients than in controls (P <0.05)." (PMID 23158556, 2012). "Blood elevation of GST-π, DJ-1, NT-proBNP, NDKA and IL6 in stroke patients were highly significant (p<.0001)." (PMID 23028472, 2012). "SDMA is positively correlated with MCP-1 at 6 and 24 hours, 3 and 7 days, with IL-6 at 3 and 7 days and with eGFR at each time point after stroke onset." (PMID 23158556, 2012). "Taken together with our earlier studies, these results show that neuroprotection by JNK inhibition occurs independently of microglial activation and IL-6 and KC secretion, an important observation in a widely used stroke model with striking neuroprotection." (PMID 22533966, 2012). "Positive correlation was established between the initial interleukin-6 content and ischemic lesion size as well as with National Institute Health Stroke Scale score on the seventh day." (PMID 21450100, 2011). "Increased levels of pro-inflammatory IL-6 are correlated with acute infarct volume measured on computed tomography (CT) and with stroke outcome measured by modified Rankin scale (mRs) at 3 months." (PMID 21871109, 2011). "Initial interleukin-6 and nitrate levels in cerebrospinal fluid found to be significant for functional outcome of stroke at one month." (PMID 21450100, 2011). "In both telmisartan- and combination pre-treated groups, protein levels of TNF-α in the ipsilateral penumbra were significantly decreased in comparison to the stroke- vehicle group, whereas IL-6 remained unchanged in all pre-treatment groups." (PMID 21901125, 2011). "Severe stroke patients had increased interleukin-6 content compared to less severe strokes (P < 0.05)." (PMID 21450100, 2011). "It is well established that inflammation is involved in stroke and that ischemia increases IL-6 concentrations in brain tissues." (PMID 21957487, 2011). "IL-6 exhibited the strongest decrease in its expression profile following stroke in aged mice brains." (PMID 22028848, 2011).
Stroke (continued). "The high EPR signal intensity resulting from the cell membrane lipids' degradation product, lipoperoxide radicals, LOO-, and the increased level of IL-6 in Group 1 indicates a prevalence of oxidative stress in severe stroke patients." (PMID 21450100, 2011). "IL-6, for example, helps to increase vascular repair and possibly neogenesis and can improve long term outcome in experimental stroke." (PMID 20356357, 2010). "IL-6 stimulates liver CRP production, an acute phase reactant associated with risk of myocardial infarction (MI) and stroke." (PMID 20543948, 2010). "The use of MEK1 inhibition might be a way to obtain anti-stroke efficiency since it targets several transcriptional mechanisms activated by cerebral ischemia: (i) receptor upregulation causing enhanced contractility, and (ii) inflammatory gene activation, i.e., for iNOS, IL-1ß, IL-6 and TNF-α." (PMID 20187933, 2010). "In clinical studies, IL-6 is often suggested as a good marker to predict the severity of an insult as high plasma levels correlate with the severity of the stroke." (PMID 21040547, 2010). "IL-6 is detected 4 hours after stroke onset, with peak concentrations after a day, and remains detectable for up to 14 days." (PMID 21040547, 2010). "Of interest, IL-10 a cytokine with strong anti-inflammatory properties and IL-6 known for its proinflammatory capacities are both elevated in stroke patients with subsequent infection." (PMID 20090932, 2010). "In this large cohort of stroke patients, we found that higher levels of IL-6, CRP, and white cell count were independently and significantly associated with poor outcome and death at 6 mo after stroke." (PMID 19901973, 2009). "The results from this study are broadly comparable to other studies of IL-6 and poor outcome or death after stroke, which supports the generalisability of the findings." (PMID 19901973, 2009). "Montaner and co-workers found positive correlations between elevated blood levels of TNFα or interleukin-6 and the volume of hypoperfused brain observed after bolus-tracking perfusion MRI studies in stroke patients." (PMID 18947406, 2008). "High levels of two biomarkers, IL-6 and PAP, did seem to identify women who were at lower risk of experiencing a stroke within the HT arms of the trial." (PMID 17571161, 2007). "Targeting immune markers, particularly IL-6 and the Th17/Treg imbalance, may offer new therapeutic approaches to improve stroke prognosis in aging populations." (PMID 41878309, 2026). "A central finding of this work is the model’s ability to reproduce the temporal decoupling between pro- and anti-inflammatory cytokines, with TNF-α and IL-6 rising sharply during the early post-stroke phase, and IL-10 emerging only after a defined temporal threshold." (PMID 41557608, 2026). "IL-6, another cytokine that promotes inflammation, is involved in various physiological and pathological processes, notably contributing in several ways to the muscle wasting seen in patients with stroke." (PMID 41598337, 2026). "Although TNF‐α shows consistent associations with stroke risk, clinical translation currently favors measuring downstream inflammatory markers (e.g., hs‐CRP and IL‐6) for prediction; TNF‐α nevertheless strengthens multimarker signatures reflective of vascular inflammation." (PMID 41567175, 2026). "Second, although the TNF-α/IL-6/IL-10 triad is central to stroke inflammation, additional mediators such as interferon-γ, MCP-1, and most notably, the critical driver IL-1β, along with cellular actors like microglia subtypes and peripheral leukocytes, are not explicitly modeled." (PMID 41557608, 2026). "We tested whether inhibition of IL-6 signaling with the IL-6 receptor (IL-6R) blocking antibody tocilizumab (TCZ) improves recovery after experimental stroke." (PMID 42146493, 2026). "IL‐6, a key cytokine in the inflammation response following cerebral ischaemia, when overexpressed, exacerbates tissue inflammation and acts as a prognostic indicator in stroke." (PMID 40448667, 2026).
Stroke (continued). "Some studies propose that IL-10 or IL-10/IL-6 ratios could serve as biomarkers to predict post-stroke complications, including infections or hemorrhagic conversion." (PMID 40869247, 2025). "This includes expanding the use of genetic instruments and Mendelian randomization to test whether specific inflammatory pathways (e.g., IL‐6 signaling, NLRP3 inflammasome activity) are causally linked to stroke risk." (PMID 41456955, 2025). "Most importantly, the included studies were not designed a priori to evaluate IL-6 as a prognostic biomarker, and the available datasets were underpowered to detect associations with rare perioperative outcomes such as stroke and death." (PMID 41440557, 2025). "Elevated IL-6 levels have indicated significant associations with higher NIHSS scores, worse mRS scores, and increased mortality at three months post-stroke, highlighting its potential utility as a prognostic biomarker for poor functional outcomes and long-term survival." (PMID 41227149, 2025). "For example, IL-6 levels begin to rise within hours after stroke onset, and persistently elevated IL-6 levels in the subacute phase may indicate ongoing inflammatory injury." (PMID 40066310, 2025). "Logistic regression analyses showed that younger age, female, higher National Institute of Health Stroke Scale score, higher interleukin-6 level, and higher hypersensitive C-reactive protein level were major predictive factors for the moderate and high symptom groups." (PMID 40709232, 2025). "Inflammation plays a pivotal role in the pathogenesis of stroke, with key mediators —specifically IL-1β (neutrophil recruitment), IL-6 (acute-phase amplification), and TNF-α (neuronal apoptosis)— confirmed to drive secondary injury and correlate with ICH severity/prognosis." (PMID 40765613, 2025). "Moreover, stroke survivors with cognitive impairment exhibit increased inflammation, with C-reactive protein, IL-6, and TNF-α serving as predictors of PSCI." (PMID 39911922, 2025). "Beyond its serotonergic modulation, preclinical evidence indicates that vortioxetine suppresses pro-inflammatory cytokines (e.g., IL-6, TNF-α) through 5-HT3 receptor antagonism and enhances synaptic plasticity via 5-HT1A receptor agonism, both mechanisms implicated in post-stroke recovery." (PMID 40144659, 2025). "Additionally, this combination therapy inhibits the increase of IL-6 levels 7 days after the stroke." (PMID 39762992, 2025). "LDH, WBC, NIHSS, and IL-6 have higher weights in both models, indicating that their roles in stroke recurrence may be significant." (PMID 40917676, 2025). "Future risk prediction models should integrate stroke-specific variables—such as the NIHSS, infarct location and size, degree of immobility, and inflammatory markers (e.g., IL-6, D-dimer)—with imaging findings to generate more accurate, individualised assessments." (PMID 40724982, 2025). "Similarly, blood and cerebrospinal fluid levels of IL6 increase following stroke and correlate with stroke severity and worse stroke outcomes." (PMID 40362325, 2025). "A similar correlation has been established for IL-6 in the cerebrospinal fluid of stroke patients." (PMID 40305179, 2025). "Notably, several outcomes in our analysis demonstrated substantial heterogeneity, including stroke (I2 = 88%), fluoroscopy time (I2 = 84%), IL-6 (I2 = 98%), and contrast volume (I2 = 89%)." (PMID 40807011, 2025). "Anti-cytokine therapies (e.g., IL-6 or TNF-α inhibitors) may also hold promise in modulating the systemic inflammatory response post-stroke." (PMID 40724982, 2025). "In the acute phase of stroke, higher IL-6 levels are detrimental to the immune system." (PMID 41368357, 2025). "However, further research is needed to better understand which IL-6 signaling pathway is utilized at different time points after stroke to effectively support patient recovery." (PMID 40305179, 2025).